UPF1 (UPF1 RNA helicase and ATPase)
Diseases named in the same sentence as UPF1 in open-access papers (continued):
Sharing a sentence is not in itself a finding about the gene and the disease.
infection (continued). "NMD inhibition (+U1D) and PEMV2 infection resulted in increased transcript levels for SMG7, SMG9, UPF1, UPF3, and CASC3, whereas HA-p26 expression increased transcript levels only for SMG7, SMG9, and UPF3." (PMID 32156817, 2020). "Here, we study NMD inhibition during infection by human T-cell lymphotropic virus type I (HTLV-1) and characterise the influence of the retroviral Tax factor on UPF1 activity." (PMID 29382845, 2018). "UPF1 does not affect the viral particle formation but is encapsidated and favors post-entry steps of the infection." (PMID 40396490, 2025). "In contrast, the abundance of transcripts, which lost UPF1 occupancy upon infection, was not significantly changed." (PMID 36603024, 2023). "Another study using a genome-wide siRNA screen in HeLa cells showed that Semliki forest virus (SFV) viral genome replication is suppressed early in infection, with involvement of UPF1, SMG5 and SMG7, but not SMG6." (PMID 36979701, 2023). "We found a significant decrease of DExH-Box Helicase 34 (DHX34), suppressor with morphogenetic effect on genitalia 5 (SMG5), and SMG7 expression at 6 h post-infection, followed by a significant increase of these genes and also UPF1 and UPF2 at 9 h post-infection." (PMID 36768954, 2023). "Cellular UPF1 protein levels were consistently downregulated by ∼50% in ZIKV-infected Huh7 cells, whereas an ∼25% reduction was observed in ZIKV-infected NPCs, mirroring the difference in infection efficiencies achieved in these two cell systems." (PMID 30401782, 2018). "It is also known that depletion of RNA decay factors like XRN1 and UPF1 doesn’t have any effect on infection of negative stranded RNA viruses of the Paramyxoviridae and Bunyaviridae families." (PMID 29494679, 2018). "Instead, the authors found that the lack of UPF1 from virus-producing cells resulted in released virions that had impaired reverse-transcription during the following round of infection." (PMID 28124995, 2017). "In the case of human immunodeficiency virus type 1 (HIV-1) for instance, two groups have shown that rather than restricting infection, UPF1 is a positive regulator of virus gene translation, vRNA nuclear export, and specific infectivity of released virions." (PMID 28124995, 2017). "In silencing-suppressed N. benthamiana, PEMV2 gRNA accumulates to rRNA levels and the extraordinary amount of viral RNA in the late stages of an infection might also enhance NMD inhibition by serving as a sink for binding to and sequestering UPF1 and possibly additional NMD factors (right)." (PMID 32156817, 2020). "Furthermore, the Gene Set Enrichment Analysis (GSEA) of UPF1-associated cellular transcripts showed that 14 gene sets were significantly enriched with UPF1 or phospho-UPF1 in EBV-infected cells, suggesting that NMD may also modulate the activity of several cellular processes during infection." (PMID 33596193, 2021). "Considering the amount of PEMV2 RNA present during an established infection, endogenous UPF1 is unlikely to have any substantial effect on PEMV2 accumulation; however, NMD surveillance would be severely impaired due to a lack of free UPF1 (right)." (PMID 32156817, 2020). "However, when compared with UPF1-unsupplemented levels (-), TCV accumulation was not enhanced by U1D, suggesting that TCV evades NMD during infection." (PMID 30452463, 2018). "Co-localization of NBAS and UPF1 proteins did not change within 24 h of infection nor did it differ in infected versus non-infected cells at 1 and 24 h after infection; similarly, the co-localization of NBAS and p31 proteins was not altered by infection in this short time frame." (PMID 36768954, 2023).
genetic diseases (2 papers, 2014 to 2024). "SRSF1 has been observed to promote nonsense-mediated mRNA decay (NMD) by recruiting UPF1, suggesting its regulatory role in gene expression and genetic diseases." (PMID 38735973, 2024). "We suggest that a better understanding of the integral role of Upf1 phosphorylation in this mRNA surveillance pathway will aid in the development of novel approaches to treat such genetic disorders." (PMID 24198248, 2014).
neurodegenerative disease (2 papers, 2011 to 2020). A disorder of the central nervous system characterized by gradual and progressive loss of neural tissue and neurologic function. "In line with our observations, several recent studies implicated the alleviation of proteotoxicity by UPF1 in neurodegenerative diseases." (PMID 32561765, 2020).
bacterial infection (1 paper, 2016). "A transient induction in UPF1 phosphorylation, peaking at 2.5 to 3 times the signal observed for unstimulated cells, occurred on treatment of RAW 264.7 macrophages with lipopolysaccharides (LPS, mimicking bacterial infection) and of NIH 3T3 fibroblasts with serum (mimicking injury)." (PMID 27511142, 2016).
haematopoietic cancer (1 paper, 2022).
UPF1 also shares sentences with these, for which no sentence is quoted: frontotemporal dementia (3 papers); depression (2); esophageal cancer (2); melanoma (2); autism spectrum disorder (1); benign tumor (1); cardiovascular diseases (1); chronic obstructive pulmonary disease (1); colitis (1); E. coli infection (1); endometrioid endometrial carcinoma (1); fatty liver (1); Hypomagnesemia (1); liver fibrosis (1); myelodysplastic syndrome (1); non-small cell lung carcinoma (1); stomach cancer (1); testicular cancer (1); thalassemia (1); thyroid cancer (1).